CD34 (CD34 molecule)
Diseases named in the same sentence as CD34 in open-access papers (continued):
Sharing a sentence is not in itself a finding about the gene and the disease.
osteosarcoma (16 papers, 2008 to 2024). A usually aggressive malignant bone-forming mesenchymal neoplasm, predominantly affecting adolescents and young adults. "Currently, there is a Phase 1 trial recruiting patients with relapsed osteosarcoma and Ewing sarcoma for a trial of treatment with C7R (functionally active CD34-IL-7R) CAR-T cells (NCT03635632)." (PMID 39086683, 2023). "We utilized three cell types for these studies: U20S osteosarcoma cell line, primary hematopoietic CD34+ CB cells, and embryonic stem (ES) cells." (PMID 34099548, 2021). "Immunohistochemical staining of the tumors with anti‐CD34 antibodies on week 8 after osteosarcoma implantation showed that the combination treatment significantly reduced the number of blood vessels in the tumors when compared with those in the other groups." (PMID 29659181, 2018). "The PROM1 gene, also known as CD133+, is one of the principal markers of osteosarcoma cancer stem cells together with CD34, a marker of the undifferentiated state of the cells, and the ALDH1A1 genes." (PMID 27651797, 2016). "Several studies have examined the clinical significance of angiogenesis-related biomarkers (VEGF, CD31, CD34, etc.)in osteosarcoma, but their results are at times in conflict and few reports relate to studies with large series." (PMID 20158913, 2010). "Since mice have different VγVδ T-cell sets than humans, to verify whether NZ could reverse chemo-immune-resistance in preclinical models of osteosarcoma, we used Hu-CD34+ mice, characterized by functional Vγ9δ2 T-lymphocytes." (PMID 32155954, 2020). "Furthermore, in our investigation,we have experienced great difficulties in the immunohistological staining byantibodies to CD34, reducing the number of cases available for statisticalanalysis regarding patient survival and recurrence of osteosarcoma." (PMID 19266050, 2008). "In this study, we investigated the role of WWOX in angiogenesis in human osteosarcoma and its effects on the expression of CD34, RUNX2, and VEGF to understand their potential interaction in the development of osteosarcoma." (PMID 28977834, 2017). "On the other hand, osteosarcoma is immunohistochemically negative for pancytokeratins 7 and 20, epithelial membrane antigens, CD34, and CD68." (PMID 35331306, 2022). "Applying chicken-specific CD34 immunohistochemistry allowed specific vessel detection, yet we were not able to fully control background staining in the CAM osteosarcoma xenografts, despite the application of several antigen retrieval and blocking techniques." (PMID 30986223, 2019).
primary myelofibrosis (16 papers, 2013 to 2024). Myelofibrosis with myeloid metaplasia is a myeloproliferative disease with annual incidence of approximately 1 case per 100,000 individuals and age at diagnosis around 60 (an increased prevalence is noted in Ashkenazi Jews). "Using this assay we found a percentage of mutated CD34+ cells ranging from 40% to 100% in Polycythemia Vera patients, from 15% to 80% in Essential Thrombocythemia and from 25% to 100% in Primary Myelofibrosis." (PMID 23865766, 2013). "MF is the most severe among the MPNs and is characterized by the occurrence of bone marrow fibrosis and a consequent abnormal increase in the number of circulating CD34+ hematopoietic progenitors." (PMID 34638230, 2021). "While this may seem problematic, data collected using CD34+ human cells from patients with either primary myelofibrosis (PMF) or essential thrombocythemia (ET) appears consistent with findings reported in this manuscript." (PMID 28783756, 2017). "Using cDNA microarray analysis of 25,100 unique genes, we studied the gene expression profile of CD34+ cells and granulocytes obtained from peripheral blood of subjects with essential thrombocythemia (ET), polycythemia vera (PV) and primary myelofibrosis (PMF)." (PMID 26275051, 2015). "To confirm that neoplastic monocyte-derived collagen- and fibronectin-producing fibrocytes induce bone marrow (BM) fibrosis in primary myelofibrosis (PMF), we injected PMF BM-derived fibrocyte-precursor CD14+/CD34- monocytes into the tail vein of NOD-SCID-γ (NSG) mice." (PMID 31569199, 2019). "Interestingly, overtPMF significantly overexpress CCR2 as compared to prePMF, suggesting that CCR2 expression on CD34+ circulating cells can be envisioned as a marker of bone marrow fibrosis (irrespective of rs1024611 SNP)." (PMID 34067466, 2021). "Of note, in these patients, the percentage of CXCL8-secreting CD34+ cells correlated with the degree of reticulin fibrosis and leukocytosis, hinting that CXCL8 secretion may serve as a biomarker for the presence of significant bone marrow fibrosis and a more aggressive disease." (PMID 37760903, 2023).
B-cell lymphoma (15 papers, 2015 to 2025). "Concerning B-cell lymphomas, CD34 expression, loss of CD44, and expression of CD5 were the most represented aberrancies in our caseload." (PMID 35448684, 2022). "With the exception of rare plasma cell tumors and some cases of B cell lymphoma, the expression of CD34 on circulating cells is considered diagnostic for acute myeloid and lymphoid leukemia, but absence of CD34 expression does not rule out the disease." (PMID 32038991, 2020). "Expression of immaturity-associated antigens such as CD34 and TdT as well as decreased expression of CD20 and CD45 are helpful in this regard (arguing for B-LL and against a mature B-cell lymphoma)." (PMID 40075660, 2025). "Archived cytology slides from 67 tissue/effusion specimens, including 27 CD34+ AL, 22 T cell lymphomas, and 18 B cell lymphomas, were retrospectively assessed." (PMID 41137732, 2025). "The response to chemotherapy of dogs with CD34+ B-cell lymphoma was poor, as it recurred during the induction (L-CHOP) protocol." (PMID 37908841, 2023). "CD34 expression has already been documented in canine B-cell lymphomas and its prognostic value investigated and excluded." (PMID 35448684, 2022). "This CD34+ clonal B-cell subpopulation was identified in established B-cell lymphoma cell lines (3 of 3) and in all patient-derived samples (8 of 8)." (PMID 32010428, 2020). "We believe that adding CD34 to MRD antibody panel in clinical studies of B-cell lymphoma will be useful in capturing this population." (PMID 32010428, 2020). "Excluding the confounding factor tumor origin, the mobilization yield of CD34+ cells for B-cell lymphoma patients was still significantly higher in the CHOP group than in the R-CHOP group (P = 0.029)." (PMID 26370464, 2015). "In another study on B-cell lymphomas, CD34+ cells were positive for CHIP-related mutations, but not for mutations frequently found in B-cell lymphomas." (PMID 38440231, 2024). "Our group identified a subset of lymphoid progenitor cells (LPCs) in primary canine B-cell lymphomas that were characterized by co-expression of hematopoietic progenitor antigens CD34, CD117, and CD133, the B-lymphoid lineage marker CD22, and the common leukocyte antigen CD456." (PMID 28357033, 2015). "In B-cell lymphoma, the most frequent aberrancies were MHC II- (53%), CD3+/CD21+ (41%), CD34+ (24%), and CD79a- (24%)." (PMID 37908841, 2023). "The most represented aberrancies in B-cell lymphoma were MHCII- (9/17, 53%), CD3+/CD21+ (7/17, 41%), CD34+ (4/17, 24%), CD79a- (4/17, 24%), while CD3+/CD21+ (5/8, 63%), CD4-/CD8- (4/8, 50%), CD45- (4/8, 50%), CD5- (4/8, 50%) were expressed in T-cell lymphoma." (PMID 37908841, 2023). "The most represented aberrancies were: CD5-, CD4-CD8-, and CD3- in T-NOS lymphomas, CD21+, CD4-CD8-, and CD3- in TZLs, and CD34+, CD44-, and CD5+ in B-cell lymphomas." (PMID 35448684, 2022). "Finally, it should be noted that the B-cell lymphomas discussed in this manuscript are mature and so (with only rare exceptions) do not express markers of immaturity (CD34 and TdT)." (PMID 40075660, 2025). "Positive expression of CD11a, CD79α, CD45, CD45RA, and MHCII and no expression of CD3, CD4, CD5, CD8, CD11d, CD14, CD21, CD34, and CD56 classifies it as a B-cell lymphoma." (PMID 27639374, 2016).
chronic GVHD (15 papers, 2015 to 2025). "In vivo graft manipulation with antithymocyte globulin (ATG) or alemtuzumab and ex vivo graft manipulation with CD34 selection and T cell depletion are strategies that are associated with lower rates of chronic GVHD." (PMID 30342553, 2018). "In a previous study, the CD34 cell dose in PBSC grafts appeared to affect the development of extensive chronic GVHD in matched sibling transplantation." (PMID 38594416, 2024). "Cox regression analysis revealed CD34+ cell counts and development of chronic GVHD as parameters to predict OS." (PMID 30717586, 2019). "Overall progress in ex vivo TCD techniques have achieved a very low incidence of GVHD, leading to a significantly lower cumulative incidence of both acute and chronic GVHD in the CD34+ group, translating in a higher GRFS in those patients." (PMID 30342553, 2018). "However, there was a trend toward reduced moderate to severe chronic GVHD in patients receiving low CD34+ cell count grafts when patients were dichotomized into low vs. high CD34+ cell counts (HR = 0.65 [0.41–1.05], p = 0.076)." (PMID 40723206, 2025). "Since higher CD3+ cell doses were independently associated with the risk of moderate to severe chronic GVHD, and there was a weak association between CD34+ and CD3+ cell counts, cell counts other than CD34+ should be considered as well for optimal treatment outcomes." (PMID 40723206, 2025). "Notably, despite younger donor age, the higher CD34+ cell dose group exhibited increased rates of chronic GVHD and NRM, which contrasts with several recent studies suggesting that younger donors are associated with a lower risk of these complications." (PMID 40773143, 2025). "Conversely, other studies have raised concerns that excessively high CD34+ cell doses may increase the risk of GVHD, particularly chronic GVHD, thereby offsetting those benefits." (PMID 40773143, 2025). "Notably, chronic GVHD was more frequently observed in the higher CD34+ cell dose group (46.2%) compared to the adequate CD34+ cell dose group (23.3%) (P = 0.048), suggesting a potential association between increased stem cell dose and a higher risk of chronic GVHD." (PMID 40773143, 2025). "Despite selecting CD34 stem cells, which helps to reduce the potential of GVHD, the risk is not completely alleviated and the incidence of acute and chronic GVHD after SCB was found to be 17% and 18% respectively." (PMID 41254453, 2025). "While six patients (7% total cohort) suffered from chronic GVHD beyond five years post-transplant, only two had moderate/severe requiring systemic treatment and defined as events, one SCID patient after a CD34 + top-up and the other following RIC MRD allograft for XLP (P15 and P20)." (PMID 35579633, 2022). "Also Urbano-Ispizua and colleagues were able to prove, using CD34+ positively selected transplantations model (which may allow to exclude the influence of CD3+), that high number of infused CD34+ cells might have a detrimental effect on NRM mainly due to higher incidence of acute and chronic GVHD." (PMID 27036034, 2016). "In the previously reported chronic GVHD in humanized mice, GVHD develops 4–5 months after transplantation of high-purity CD34-positive cells containing almost no peripheral blood T-cells, suggesting that GVHD developed by a mechanism different from that in the existing experimental mouse models." (PMID 34825089, 2021).
fibrous tumors (15 papers, 2013 to 2025). "Solitary fibrous tumor, which rarely arises in the dermo-hypodermic area, also expresses CD34, raising differential diagnostic problems with DFSP." (PMID 33445443, 2021). "Later on, there were reports of gastrointestinal CD34+ ‘fibrous tumors’ with an uncertain classification in the presence of a germline PDGFRA mutation." (PMID 38305808, 2024). "This rare medical condition is classified as superficial CD34-positive fibroblastic tumor (SCPFT), an intermediate form of mesenchymal malignancy, originally identified in medical literature in 2014." (PMID 37692690, 2023). "CD34 clearly demarcates fibrocytes in the adventitia, which is in line with previous studies, and the use of CD34 as a marker for the diagnostics of fibrous tumors." (PMID 27764183, 2016). "Solitary fibrous tumors consist of spindle cells and they are positive for vimentin and CD34 in contrast with glomus tumors." (PMID 26442165, 2015). "The introduction of CD34 has facilitated the recognition of both benign and malignant intrathoracic, fibrous tumors." (PMID 24267748, 2013). "Solitary fibrous tumors share CD34 expression but are rare in the GI tract and lack inflammation." (PMID 41562800, 2025). "Solitary fibrous tumor may be differentiated from myofibroma because its neoplastic cells express CD34." (PMID 25918649, 2015). "After a tumor resection, microscopic findings were spindled tumor cells with reactivity to CD34, bcl-2 and CD99 and the tumor was diagnosed as Solitary Fibrous Tumor." (PMID 25136435, 2014). "Immunohistochemical stains for pan-cytokeratin, DOG1, desmin, S100, CD34, and MUC4 were negative, and a diagnosis of the calcifying fibrous tumor was rendered." (PMID 36186113, 2022). "Solitary fibrous tumor is rich in collagen and, differently from GPC, tumor cells are positive to bcl-2 and negative to CD34 and actin." (PMID 25143851, 2014).
infarction (15 papers, 2011 to 2024). A localised pathological necrosis of tissue resulting from obstruction of the blood supply usually by a thrombus, an embolus, or vascular torsion. "Experiment 1 showed intravenous infusion with CD34+ cells before MCAO (pre-treatment) caused less infarction size than those infused after MCAO (post-treatment) on 7T magnetic resonance T2-weighted images." (PMID 26760774, 2016). "On the other hand, pre- and post-treatment with Avemar caused a greater significant increase in CD34+ cell homing by 268 % (P < 0.001) on day 14 after infarction development than in the AMI group." (PMID 26369808, 2015). "CD34+ EPCs isolated from human peripheral blood have also been shown to be of potential therapeutic use in myocardium infarction rat models by contributing to the post-infarction neovascularization and aiding to improve the associated symptoms." (PMID 33193725, 2020). "Among the three pre-treatment groups, pre-treatment with E2+CD34+ had the least infarction volume and showed significant difference when compared with E2 pre-treatment groups (p = 0.031)." (PMID 26760774, 2016). "When CD105+CD34- cells were administrated into the border area of the post-infarction scar they retain their ability to IL-6 secretion." (PMID 27415778, 2016). "In mice injected with CD105+CD34- cells 7 days after MI, a statistically significant reduction in the size of post-infarction scar (22.53±5.55%) compared to the control PBS- group (32.84±3.76%; p<0.01) was observed." (PMID 27415778, 2016). "The data from the current study revealed that treatment with Avemar or Echinacea pre- and post-infarction efficiently induced great mobilization of CD34+ cells from their niches on day 1 and 14 after AMI." (PMID 26369808, 2015). "In this study, induction of AMI using isoprenaline resulted in increased circulating CD34+ cells with a peak on day 14 from infarction development." (PMID 26369808, 2015). "On the other hand, homing of CD34+ cells at the myocardium in response to treatment was accompanied by higher expression of α-SMA 14 days after infarction." (PMID 26369808, 2015). "We have developed a new platform to enhance the survival of CD34+ cells using a natural and cost-effective ligand and demonstrated its utility in the preservation of the functionality of the heart after infarction." (PMID 26553339, 2015). "Recruitment of monocytes/macrophages was significantly enhanced in human CD34+-transplanted murine hearts after infarction and this effect seems to be mediated by human cytokines MCP-1 and IL-845." (PMID 26553339, 2015). "Our results indicated that CD34+ cell-derived ECs exhibited active proliferative capacity, which may be beneficial to post-infarction angiogenesis and restoration of local microcirculation, thereby to some extent limited the infarct area." (PMID 37147443, 2023). "In the present study, we simulated myocardial ECM stiffness at different time points after infarction using an in vitro system, and investigated the effect of matrix stiffness as well as the expression of the cell surface marker CD34 of BMMNCs on endothelial lineage commitment." (PMID 29237495, 2017). "Our results call for a generalized increase of CD34+ cells cardioprotection ability or an improved “paracrine effect” that may sustain cardiac contractility or interfere with myocardial cells apoptosis as short times after infarction." (PMID 21789227, 2011). "Moreover, the CD34+ cell subset was prone to effective specification into endothelial lineage cells under induction on a matrix with a stiffness of 42 kPa (corresponding to myocardial ECM stiffness at 7–14 days post-infarction) than with other matrix stiffnesses." (PMID 29237495, 2017). "In the area of post-infarction scar, where CD105+CD34- cells were transplanted, we observed the influx of M2 macrophages (cells with F4/80+CD206+ phenotype)." (PMID 27415778, 2016).
infarction (continued). "The result showed the infarction volume was significantly smaller in CD34+ pre-treatment group (84.94 ± 37.14 mm3) than no treatment group (177.22 ± 28.39 mm3, p = 0.011) on T2-weighted images obtained at 2 d after MCAO." (PMID 26760774, 2016). "Reperfused AMI led to an increase in CXCR4, but not SDF-1α, at 3 days post-infarction, with moderate enhancement of circulating CD34+ counts." (PMID 28299177, 2016). "Our in vivo results show that LPA-treated CD34+ cells have superior survival than non-treated cells, hence being able to contribute to the preservation of cardiac function after infarction." (PMID 26553339, 2015). "On the other hand, animals that received Avemar only after infarction development exhibited no change in the mobilization of SCs, while those receiving Echinacea showed more circulating CD34+ cells on days 7 and 14 compared to their corresponding AMI values." (PMID 26369808, 2015). "We observed a significant parallel increase of mobilized CD34+ cells in both non-conditioned AMI and IP groups 3 days post infarction (IP: 881±126 vs. control: 668±180cells/μl; P=0.026, returning to the baseline level after 1 month FUP (IP: 255±50 vs. control: 275±118cells/μl; P=0.85)." (PMID 28299177, 2016).